GRM1 (glutamate metabotropic receptor 1)
Diseases named in the same sentence as GRM1 in open-access papers (continued):
Sharing a sentence is not in itself a finding about the gene and the disease.
breast carcinoma (continued). "Therefore, we undertook a study to evaluate SNPs in GRM1 for correlation with development of specific breast cancer molecular subtypes and age at diagnosis." (PMID 23922822, 2013). "As one potential cause of earlier age at diagnosis of breast cancer may reflect faster growing tumors, the effect of GRM1 expression on breast cancer cell growth was evaluated." (PMID 23922822, 2013). "Associations between GRM1 expression in breast tumors and breast cancer outcomes have not been previously reported." (PMID 23922822, 2013). "Given the correlations between GRM1 SNP genotypes and hormone receptor status, GRM1 expression was evaluated in a set of breast tissue microarrays for correlation with molecular features of breast cancer, e.g. receptor status." (PMID 23922822, 2013). "The fact that GRM1 expression is prominent in malignant breast tissue as compared to normal breast tissue suggests that altered GRM1 expression occurs in the development of breast cancer." (PMID 23922822, 2013). "Taken together, these findings suggest a functional role for GRM1 in breast cancer." (PMID 23922822, 2013). "The prognostic value of mGluR1/GRM1 expression in other breast cancer subgroups is unknown." (PMID 33339858, 2020). "Additionally, measurement of cell proliferation by MTS assay produced similar results suggesting that GRM1 may be an important regulator of breast cancer cell growth." (PMID 23922822, 2013). "No studies have evaluated SNPs in GRM1 and risk of breast cancer." (PMID 23922822, 2013). "Activation of GRM1 leads to increased MAPK and AKT activities where both are known to contribute to resistance to breast cancer endocrine therapies including tamoxifen." (PMID 23922822, 2013). "Here, in the present study, we identified the regulation of the FoxO signaling pathway via the modulation of four genes i.e. MDM2, STAT3, IGF1R, and GRM1 which could support the functioning of the PI3K-Akt and EGFR signal against breast cancer pathogenesis." (PMID 36686654, 2022). "Interestingly, MDA-MB-231 triple-negative breast cancer cells and normal AB589 mammary epithelial cells express GRM1; however, treatment of cells with the mGluR1 antagonist BAY 36-7620 had a significant effect on cell growth only in breast cancer cells." (PMID 36457557, 2022). "ER positive and negative breast cancer cell lines were evaluated for GRM1 expression by Western blot." (PMID 28591718, 2017). "As expected, no changes in GRM1 expression were observed in the hormone receptor negative MDA-MB-231 breast cancer cell line with any of the hormonal treatments." (PMID 23922822, 2013). "There were no genotype-specific differences in histologic subtype of breast cancer for either GRM1 locus." (PMID 23922822, 2013). "In this only study describing GRM1 in breast cancer, ER+ breast cancer cells were not evaluated." (PMID 23922822, 2013). "Therefore, a study was undertaken to investigate the functional actions of riluzole, in comparison to the known noncompetitive GRM1 inhibitor BAY 36-7620, on a molecularly diverse panel of breast cancer cells." (PMID 28591718, 2017).
epilepsy (19 papers, 2012 to 2026). A brain disorder characterized by episodes of abnormally increased neuronal discharge resulting in transient episodes of sensory or motor neurological dysfunction, or psychic dysfunction. "Gene grm1 encodes a metabotropic glutamate receptor (mGluR), which is a second-messenger coupled receptor involved in neuronal plasticity and epilepsy." (PMID 34925021, 2021). "Epilepsy-related proteins, including upregulation of GRM1 and COMT and downregulation of PDGFRB and OTX2, were noted." (PMID 41597222, 2026). "Ultimately, 5 target genes were obtained, of which P2RX7 and TMTC2 were upregulated and CACNA1C, JPH3 and GRM1 were downregulated in epilepsy." (PMID 38191407, 2024). "Additionally, the mediumblue module (Pvalb subtypes, 173 genes), while not passing the test for associating more strongly with epilepsy than with any sample, included the genes GRIK1, GRIK2, GRIK4, GRM1, GRM7, and GRIA1, suggesting a potential involvement in glutamate receptor subunits." (PMID 33028830, 2020).
Anxiety (15 papers, 2008 to 2025). Intense feelings of nervousness, tension, or panic often arise in response to interpersonal stresses. "To address this hypothesis, we designed three shRNAs and cloned them into adeno‐associated virus vector to directly knockdown DSS‐induced Grm1 expression in the hippocampus to examine the effect of this knockdown on anxiety behavior impact." (PMID 38676295, 2024). "Our proteomic analysis further indicates that upregulated Grm1 expression correlates with cognitive deficits and anxiety-like behaviors." (PMID 41150532, 2025). "Our results demonstrate for the first time that inhibition of hippocampal mGluR1 (GRM1) improves anxiety‐like behavior in DSS‐induced colitis mice." (PMID 38676295, 2024). "We also demonstrate for the first time that the hippocampal glutamate metabolizing receptor GRM1 is an important central target of colitis‐induced anxiety behaviors." (PMID 38676295, 2024). "Since numerous studies have reported that GRM1 induces anxiety‐like behaviors in various animal models, we examined the expression of Grm1 in the hippocampus." (PMID 38676295, 2024). "After clarifying the inhibitory effect on hippocampal GRM1, the effect of AAV‐Grm1‐shRNA on anxiety‐like behavior was measured." (PMID 38676295, 2024). "Peripheral suppression of colon inflammation or downregulation of GRM1 expression by AAV virus interference can significantly improve anxiety‐like behavior." (PMID 38676295, 2024). "Inflammation inhibitor TAK‐242 can significantly inhibit the expression of hippocampal GRM1 and significantly improve anxiety‐like behavior in colitis mice." (PMID 38676295, 2024). "Our work suggests that the hippocampus plays an important role in brain anxiety caused by peripheral inflammation, and over‐excitation of hippocampal glutamate synapses by GRM1 activation induces anxiety‐like behavior in colitis mice." (PMID 38676295, 2024). "Spatial transcriptome analysis of the hippocampus showed an excitatory‐inhibitory imbalance mediated by glutamatergic synapses, and GRM1 in hippocampus was identified as a critical mediator of anxiety behavior in colitis mice via differential gene screening and AAV virus interference." (PMID 38676295, 2024). "RT‐qPCR and IF results showed that Grm1 was significantly upregulated in the hippocampus of colitis mice, suggesting that it may be a critical target of peripheral inflammation‐induced anxiety behavior." (PMID 38676295, 2024). "Finally, we demonstrate that glutamate‐metabolized receptor GRM1 is directly involved in inflammation‐induced anxiety processes and that peripheral suppression of colon inflammation or downregulation of GRM1 expression by AAV virus interference can significantly improve anxiety‐like behavior." (PMID 38676295, 2024). "GRM1 and GRM5 are type I metabotropic glutamate receptors involved in various mental illnesses, including depression, anxiety, and cognitive impairment by regulating the function of neurotransmitters such as glutamate, dopamine, and norepinephrine." (PMID 36210820, 2022). "Last but not at the least, to better understand the relationship of anxiety‐behavior and the expression of GRM1, the concentration of TAK‐242 in serum and cerebral should be monitor in the future research." (PMID 38676295, 2024).
depression (13 papers, 2007 to 2024). "We next sought to determine which formulation was superior in treating mild-to-moderate COVID-19 with symptoms of depression or inflammation via targeting specific targets (GRM1, GRM5, mTOR and PLA2G4A)." (PMID 36210820, 2022).
autism (12 papers, 2016 to 2025). Persistent deficits in social interaction and communication and interaction as well as a markedly restricted repertoire of activity and interest as well as repetitive patterns of behavior. "Cells in the later pseudotime stage exhibited specific enrichment in synaptic pathways, characterized by the upregulation of several neuronal markers, including CUX2, glutamate metabotropic receptor genes (GRM1, GRM2, and GRM3), and several autism risk genes, including PTEN, SCN2A, and SHANK2." (PMID 39363111, 2024).
glioma (12 papers, 2009 to 2025). A benign or malignant brain and spinal cord tumor that arises from glial cells (astrocytes, oligodendrocytes, ependymal cells). "Metabotropic glutamate receptor 1 (GRM1), 5-Hydroxytryptamine (serotonin) receptor 7 (HTR7), and 5-Hydroxytryptamine (5-HT) receptor 2A (HTR2A) may play a role in glioma by participating in the interaction pathway of neuroactive ligand receptor interaction pathway." (PMID 36980973, 2023). "In addition, GRM1 and adenylate cyclase 2 (ADCY2) may contribute to glioma development through the calcium signaling pathway." (PMID 36980973, 2023).
triple-negative breast carcinoma (11 papers, 2013 to 2024). An invasive breast carcinoma which is negative for expression of estrogen receptor (ER), progesterone receptor (PR), and human epidermal growth factor receptor 2 (HER2). "In triple-negative breast cancer cells, both a selective mGluR1 antagonist and silencing with shRNA targeting the gene GRM1 inhibited proliferation associated with apoptosis." (PMID 36457557, 2022). "Analysis of the progression from normal epithelium to triple-negative breast cancer demonstrated that mGluR1 overexpression induces transformation to a malignant phenotype that was reverted by silencing the GRM1 gene." (PMID 36457557, 2022). "Metabotropic glutamate receptor-1 (GRM1) has been reported as an oncogene in the progression of triple negative breast cancer, whose alteration may affect the pathway Alanine, aspartate and glutamate metabolism." (PMID 25041817, 2014).
prostate carcinoma (9 papers, 2014 to 2025). A carcinoma that arises from epithelial cells of the prostate gland. "Additional investigations are needed to assess the consequences of these single nucleotide polymorphisms in GRM1 in prostate cancer development and progression." (PMID 36139432, 2022). "Genotype status of non-synonymous and synonymous mutations and polymorphisms identified in GRM1 gene in prostate cancer cell lines." (PMID 25062106, 2014). "Metabotropic glutamate receptor 1 (GRM1) signaling has been implicated in benign and malignant disorders including prostate cancer (PCa)." (PMID 25062106, 2014). "Genotype status of downstream non-coding polymorphisms identified in GRM1 gene in prostate cancer cell lines." (PMID 25062106, 2014). "Ali and colleagues described single nucleotide polymorphisms of GRM1 that may affect splicing, ligand binding, and downstream signaling in prostate cancer cells." (PMID 36139432, 2022). "In addition, mutations and single nucleotide polymorphisms (SNPs) of GRM1 were described in prostate cancer and eight somatic variations of GRM1 were identified in cancers, including lung adenocarcinoma." (PMID 28212543, 2017).
metastatic melanoma (7 papers, 2018 to 2024). A melanoma that has spread from its primary site to another anatomic site. "We had previously demonstrated that aberrant expression of GRM1 (metabotropic glutamate receptor 1) in melanocytes is sufficient to induce spontaneous metastatic melanoma in mice." (PMID 30425240, 2018). "In humans, GRM1 expression is not detected in normal melanocytes but it is expressed in 80% of metastatic melanoma or cell lines." (PMID 35158973, 2022). "Surprisingly, the mouse developed metastatic melanoma, whereas Grm1 is not detected in normal melanocytes in mice." (PMID 35158973, 2022). "In vivo investigations were conducted using the Grm1-Tg transgenic mouse strain that develops spontaneous metastatic melanoma, which was crossed with SELENOK−/− mice to generate the following littermates: Grm1-Tg/SELENOK−/−, Grm1-Tg/SELENOK−/+, Grm1-Tg/SELENOK+/+." (PMID 29568366, 2018).
lung carcinoma (6 papers, 2013 to 2025). "Grm1 was upregulated in LUSC, suggesting that this gene participates in lung cancer development." (PMID 31921388, 2019).
amyotrophic lateral sclerosis (4 papers, 2016 to 2024). Amyotrophic lateral sclerosis (ALS) is a neurodegenerative disease characterized by progressive muscular paralysis reflecting degeneration of motor neurons in the primary motor cortex, corticospinal tracts, brainstem and spinal cord. "Similarly, inhibition of glutamate release by riluzole, a drug approved by the US FDA for the treatment of amyotrophic lateral sclerosis (ALS), suppresses proliferation of GRM1-positive human tumor cells in vitro and tumor progression in vivo." (PMID 30425240, 2018).
chondromyxoid fibroma (4 papers, 2014 to 2025). An uncommon benign cartilaginous neoplasm arising from the bone. "GRM1 can serve as a histological marker for distinguishing chondromyxoid fibroma." (PMID 40452916, 2025). "In about 90% of tumors, the genetic driver event involves a mutation in the glutamate receptor gene, GRM1, which seems unique to chondromyxoid fibroma and is rare to absent in other cartilaginous tumors." (PMID 38892944, 2024).
fragile X syndrome (4 papers, 2011 to 2023). A genetic syndrome caused by mutations in the FMR1 gene which is responsible for the expression of the fragile X mental retardation 1 protein. "GRM1 has a well-established role in the commonest form ofmental retardation, Fragile X syndrome." (PMID 21559497, 2011).
autosomal recessive spinocerebellar ataxia 13 (3 papers, 2015 to 2025). "Most importantly, autosomal recessive spinocerebellar ataxia-13 (SCA13) has been found to be caused by a complex homozygous mutation in the GRM1 gene encoding mGluR1 that results in aberrant transcripts lacking important functional domains." (PMID 26377085, 2015). "Autosomal recessive spinocerebellar ataxia 13 (SCAR13; MIM 614831) is an ultra-rare disorder caused by pathogenic or disruptive mutations in the GRM1 gene, located on chromosome 6q24.3." (PMID 40858856, 2025).
breast tumors (3 papers, 2013 to 2017). "Consistent with higher GRM1 expression in malignant as compared to normal prostate tissue, a significantly higher fraction of human breast tumors express GRM1 as compared to normal breast tissue." (PMID 28591718, 2017). "TMA analysis of GRM1 expression in breast tumors further confirmed the correlation between hormone receptor status and GRM1 expression." (PMID 23922822, 2013). "Evaluation of GRM1 expression in human breast tumor specimens demonstrated significant correlations between GRM1 staining with tissue type and molecular features." (PMID 23922822, 2013). "Furthermore, in primary estrogen receptor positive human breast tumors with high GRM1 expression, there was shorter distant metastasis-free survival with tamoxifen treatment." (PMID 23922822, 2013). "Furthermore, analysis of gene expression data from primary breast tumors showed that high GRM1 expression correlated with a shorter distant metastasis-free survival as compared to low GRM1 expression in tamoxifen-treated patients." (PMID 23922822, 2013).
Cerebellar atrophy (3 papers, 2016 to 2025). Cerebellar atrophy is defined as a cerebellum with initially normal structures, in a posterior fossa with normal size, which displays enlarged fissures (interfolial spaces) in comparison to the foliae secondary to loss of tissue. "Another related member, GRM1, causes autosomal recessive spinocerebellar ataxia type 13 (MIM#614831) which may include cerebellar atrophy." (PMID 27435318, 2016).
cutaneous melanoma (3 papers, 2012 to 2025). A primary melanoma arising from atypical melanocytes in the skin. "Although in skin melanoma, the amount of cDC1 cells is low, e.g., in tg(Grm1)EPv mice, the amount of cDC1 positive cells in skin melanomas was less than 1% of the CD45+ cells, compared to more than 2% cDC2 and about 8% Langerhans cells, cDC1 still had important anti-tumoral effects." (PMID 35163401, 2022). "Grm1-transgenic mice spontaneously develop cutaneous melanoma." (PMID 22674057, 2012).
diabetes (3 papers, 2018 to 2026). "SIRT1 has been reported to attenuate neuropathic pain in diabetes through suppression of mGluR1/5 by facilitating H3 acetylation at the promoter region of mGluR1/5-encoding Grm1/5." (PMID 34071497, 2021).
neuroblastoma (3 papers, 2013 to 2022). Neuroblastoma (NB) is the most common solid, extracranial childhood tumor. "In flow-cytometry analysis, down-regulation of postsynaptic density and dendrite spine morphology regulatory proteins (ARC, NMDAR1 and GRM1) was confirmed in both clade B and C infected primary human astrocytes and SK-N-MC neuroblastoma cells." (PMID 23620748, 2013). "Similarly, we have also observed significantly decreased expression of ARC, NMDAR1 and GRM1 proteins in clade B and C infected SK-N-MC neuroblastoma cells than the control cells (data not shown)." (PMID 23620748, 2013).
bone cancer (2 papers, 2023 to 2024). A primary or metastatic malignant neoplasm affecting the bone or articular cartilage. "A recent study showed that GRM1 immunohistochemistry may be a useful ancillary technique to confirm the diagnosis of CMF and to differentiate it from morphological mimics, since it is not expressed in other bone tumours, which may be considered in the differential diagnosis with CMF." (PMID 36810795, 2023).
cognitive decline (2 papers, 2026). "Some previous GRM1-related SCA exhibited spasticity, but none reported cognitive decline." (PMID 40940404, 2026).
colon adenocarcinoma (2 papers, 2014 to 2016). "We have identified DYNC1H1,GRIN2A, and GRM1 as novel hub driver genes for the stage-II progression of colon adenocarcinoma." (PMID 27243824, 2016).
liver cancer (2 papers, 2017 to 2021). An epithelial or non-epithelial malignant neoplasm that arises from the liver. "Moreover, we could show an impact of exercise on tumor size and incidence on liver cancer using a diethylnitrosamine (DEN) induced liver cancer model, as well as the spontaneous melanoma model GrM1." (PMID 28324125, 2017).
thyroid cancer (2 papers, 2014 to 2024). "We found multiple instances of glutamate receptors (e.g., GRM1, 2, 4, 5) and glutamate decarboxylase 1 and 2 (GAD1, 2), with the axes of GAD2 with GRM1, 4 and 5 being always significantly associated with lower survival in endometrium and thyroid cancer tissues." (PMID 38723607, 2024).
Aleutian disease (1 paper, 2024). "From this, we identified several candidate genes contributing to the growth and feed efficiency (ARID1B, APPL1, TOX, and GPC5), reproduction (GRM1, RNASE10, WNT3, WNT3A, and WNT9B), pelt quality (MYO10, and LIMS1), and Aleutian disease tests (IFNGR2, APEX1, UBE3A, and STX11)." (PMID 38167844, 2024).
autosomal dominant spinocerebellar ataxias (1 paper, 2023). "Mutations in the GRM1 gene have previously been known to cause autosomal recessive and autosomal dominant spinocerebellar ataxias." (PMID 36675067, 2023).
cardiac hypertrophy (1 paper, 2020). "DRD1 and GRM1, the genes that were downregulated at all time points, have not previously been linked specifically to cardiac hypertrophy but based on our results may merit further investigation in this context." (PMID 32878883, 2020).
cerebral malaria (1 paper, 2025). A sequestration of Plasmodium falciparum in the brain, which can cause coma and/or seizures. "Glutamate Metabotropic Receptor 1, which is primarily involved in neuronal glutamate signaling, also contributes to neuroinflammatory processes central to the pathogenesis of cerebral malaria by regulating brain-specific inflammatory responses." (PMID 41333726, 2025).
colitis (1 paper, 2024). Inflammation of the colon. "We also found that hippocampal glutamate metabotropic receptor Grm1 has a spatially differential expression pattern similar to glutamate synaptic signaling, and interfering with Grm1 expression can significantly improve anxiety behavior in colitis mice." (PMID 38676295, 2024).